IGF1R (insulin like growth factor 1 receptor)
Diseases named in the same sentence as IGF1R in open-access papers (continued):
Sharing a sentence is not in itself a finding about the gene and the disease.
lung cancer (continued). "Similarly, tyrosine kinase inhibitors like linsitinib, picropodophyllin, and BMS-754807 can also target IGF-1R for lung cancer therapy." (PMID 38540176, 2024). "IGF-1R is also known for its oncogenic potential, which means that its abnormal activation or overexpression can contribute to the development and progression of various cancer types, including lung cancer." (PMID 38540176, 2024). "In addition to the impact of IGF-1R on the development and progression of lung cancer, there is compelling evidence indicating that the IGF/IGF-1R axis plays a significant role in cancer treatment resistance." (PMID 38540176, 2024). "Therefore, more investigations are needed in this area to determine the safest and most effective application of IGF/IGF-1R inhibitors as a therapy for lung cancer." (PMID 38540176, 2024). "Interestingly, overexpression of IGF1R within the tumour microenvironment was reported to promote tumour initiation and progression in lung cancer and medulloblastoma." (PMID 39167619, 2024). "Therefore, the potential use of IGF1R-targeting strategies in lung cancer has been considered in several preclinical studies and clinical trials." (PMID 38200153, 2024). "PRKCSH abundance is correlated with IGF1R upregulation in lung cancer tissues." (PMID 38200153, 2024). "Specifically, insulin-sensitizing agents and inhibitors of insulin-like growth factor-1 receptor (IGF-1R) have been investigated as potential treatments for lung cancer, aiming to inhibit aberrant signaling and cell proliferation associated with insulin resistance." (PMID 38449844, 2024). "This underscores the need to address IGF-1R signaling within lung cancer treatment." (PMID 38540176, 2024). "However, despite these important considerations, the IGF/IGF-1R signaling axis still holds much promise as a potential candidate for future cancer therapeutic interventions, especially for lung cancer." (PMID 38540176, 2024). "IGF1R may serve as a prognostic indicator and a guide for perioperative treatment strategies in early-stage lung cancer." (PMID 39365756, 2024). "In addition, the lack of IGF1R or ITGAV renders epithelial cancer cells insensitive to TGFβ-mediated EMT induction, as demonstrated in lung cancer cells following IGF1R inhibition." (PMID 39075581, 2024). "Subsequently, we analyzed IGF1R mRNA expression levels at different stages of lung cancer." (PMID 38200153, 2024). "PRKCSH depletion promoted the interaction between HERPUD1 and IGF1R in lung cancer cells." (PMID 38200153, 2024). "Previous studies indicated that EGFR and IGF1R are essential in lung cancer progression." (PMID 37880793, 2023). "Moreover, lnc-MLETA1 expression was positively correlated with EGFR and IGF1R expression in lung cancer tissues." (PMID 37880793, 2023). "✓ Gefitinib combined with miR-30A-5p mimics, could suppress the growth in acquired TKI resistance lung cancer cells via IGF1R and HGFR signaling." (PMID 37152062, 2023). "Moreover, miR-186-5p and miR-497-5p expression was negatively correlated with expression of the target genes EGFR and IGF1R in lung cancer tissues, respectively." (PMID 37880793, 2023). "Conclusively, IGF1R might participate in the regulation of the THRIL/miR-99a axis in the lung carcinoma cell line." (PMID 37582734, 2023). "Additionally, it can target IGF-1R in gastric cancer and suppress the fibroblast growth factor receptor 3 gene in lung cancer." (PMID 36293349, 2022). "For instance, in epidermal growth factor receptor (EGFR)-mutant lung cancer, activation of the Hippo pathway effector protein YAP, Notch-3/β-catenin signaling, AXL, insulin-like growth factor 1 receptor (IGF-1R), or BIM deletion polymorphism mediates drug persistence to initial EGFR-TKI treatment." (PMID 35228642, 2022).
lung cancer (continued). "Exosomes from dormant lung cancer cells enhanced the glycolysis of BMSCs through IGF-1R signaling." (PMID 36568212, 2022). "We do observe that FOXA1 expression help to maintain the phosphorylation status of IGF1R signaling cascade of lung cancer cells in the serum starvation conditions, which might be explained by increased IGF2 autocrine in lung cancer cells by FOXA1." (PMID 35974000, 2022). "Inhibition of IGF-1R or glycolysis can reduce the lung cancer cell growth in the bone marrow." (PMID 36568212, 2022). "However, apart from prostate cancer, only one study in nonsmall cell lung cancer found 59 downregulated miRNAs by silencing the insulin-like growth factor 1 receptor (IGF-1R) gene, and MIR6750 has been shown to be downregulated." (PMID 33550766, 2021). "Moreover, the disruption of IGF-II/IGF1R signaling represses Nanog expression and restrains cancer stem-like features in lung cancer." (PMID 33407730, 2021). "Furthermore, we clinically verified the PKM2-regulated expression of IGF-1R from lung cancer patient tissues, which exhibited a significant positive correlation (r = 0.6031, p < 0.0001) between PKM2 and IGF-1R expression." (PMID 34359752, 2021). "Subsequent to the first report of IGF-1R activation in 2010, AXL, Notch3, and fibroblast growth factor receptor 3 (FGFR3) are identified as receptor tyrosine kinases (RTKs) that cause drug tolerance in lung cancers with EGFR mutations." (PMID 34202566, 2021). "In contrast, in EGFR-mutated lung cancer cell lines expressing low levels of AXL (HCC827, HCC4006, and H3255 cells), EGFR TKI tolerance was mediated by an insulin-like growth factor-1 receptor (IGF-1R) through the induction of its transcription factor FOXA1." (PMID 34202566, 2021). "Circ‐IGF1R may inhibit lung cancer invasion and migration through a network of circ‐IGF1R–miR‐1270–VANGL2." (PMID 32107851, 2020). "Circ‐IGF1R may inhibit lung cancer invasion and migration through a potential network of circ‐IGF1R–miR‐1270–VANGL2." (PMID 32107851, 2020). "Therefore, IGF1R is considered an emerging target for lung cancer treatment, and IGF1R-targeted agents are in advanced stages of clinical development." (PMID 32971893, 2020). "In this study, we aimed to study the mechanism of action of circ‐IGF1R in lung cancer." (PMID 32107851, 2020). "The mechanism of action of hsa_circ_0005035 (circ‐IGF1R) in non‐small cell lung cancer remains unclear." (PMID 32107851, 2020). "Moreover, we assessed the death risk of lung cancer patients using 4 target genes related to let-7a-5p, including BCL2L1, IGF1R, MAPK8, and FAS." (PMID 31508368, 2019). "High expression of BCL2L1 elevated lung cancer patients death risk [hazard ratio (HR) and 95% confidence intervals (CI) = 1.60(1.38–1.86)], but no similar correlations were found in IGF1R, MAPK8, and FAS." (PMID 31508368, 2019). "It found that procyanidins could activate insulin-like growth factor-1 receptor (IGF-1R) phosphorylation and cysteine protease, inhibit the activity of Nrf2-regulated enzymes and the level of Nrf2 expression in lung cancer cells." (PMID 31557828, 2019). "Ceritinib is approved for ALK-positive lung cancer and can also inhibit IGF1R." (PMID 31234291, 2019). "Because lung cancer cells may overexpress IR-A and IGF-1R, the binding of insulin to these receptors triggers the mitogenic pathways." (PMID 31354621, 2019). "Moreover, ceritinib, which is approved for anaplastic lymphoma kinase (ALK) positive lung cancer, can also inhibit IGF1R and INSR." (PMID 31480400, 2019). "Activation of IGF1R has been found in several types of human cancer, including lung cancer." (PMID 29455661, 2018).
lung cancer (continued). "As a result, expression of BCL2L1 and IGF1R were found to be increased in all lung cancer subtypes." (PMID 30497474, 2018). "After a couple of years of this experiment, IGF-1R targeted shRNA with super-paramagnetic iron-oxide nanoparticles (SPIONs) under the influence of magnetic field silenced 86% of IGF-1R gene expression in the same lung cancer model." (PMID 29861465, 2018). "Our results also support the hypothesis that ALK and IGF-1R are independent druggable targets in ALK-positive lung cancer." (PMID 29066738, 2017). "In this study we investigated whether IGF-1R is an independent druggable target in ALK-positive lung cancer cells." (PMID 29066738, 2017). "For example, patients with TNBC or KRAS-mutant lung cancers may obtain optimal benefit from IGF1R inhibitor drugs." (PMID 29099049, 2017). "The authors also proposed that the efficacy of ceritinib against crizotinib resistant lung cancer might be partially explained by its dual IGF-1R/ALK inhibitory action." (PMID 29066738, 2017). "The in vitro manipulation of human lung tumor cells also supports the idea that Igf1r is a critical regulator of lung tumorigenesis since targeting the IGF-IR protein inhibits lung tumor cell proliferation and sensitizes lung cancer cells to chemotherapy and radiotherapy." (PMID 26654940, 2016). "The SPC-IGFIR transgenic mouse model is relevant to lung cancer since IGF-IR is highly expressed in ∼95% of human SCLCs and ∼80% of NSCLCs and high levels of Igf1r mRNA have been significantly associated with reduced overall survival and disease-free survival in NSCLC." (PMID 26654940, 2016). "A total of three lung cancer studies were identified from the TCGA Research Network portal including TCGA provisional data, TCGA Nature 2012, and TCGA Nature 2014 data for IGF-1R mRNA and protein expression." (PMID 25944691, 2015). "The analysis verified the important contribution of IGF-1R or c-Met in the drug resistance mechanism developed in lung cancer treatments, which may bring many benefits to specialized therapy design and innovative drug discovery." (PMID 25993617, 2015). "For example, patients with triple negative breast cancer or KRAS-mutant lung cancers might benefit from IGF-1R inhibitor drugs." (PMID 26217584, 2015). "Inactivation of Trop2 may play a role in lung cancer tumorigenicity through losing its suppressive effect on IGF-1R signaling and tumor growth." (PMID 26000093, 2015). "In Wilms' tumor, WT1 suppresses the IGF-1R gene, while Trop2 lowers IGF-1R levels in lung cancer." (PMID 26000093, 2015). "Furthermore, EFEMP1 suppresses both the epithelial-to-mesenchymal transition and self-renewal of lung cancer stem cells by modulating the IGF1R/PI3K/AKT/GSK3β pathway." (PMID 25987128, 2015). "The use of an IGF-1R inhibitor is a potential new strategy in the treatment of lung cancer." (PMID 26793618, 2015). "Our results suggest that TM4SF4 overexpression in lung carcinoma cells results in resistance to radiotherapy via IGF1-induced IGF1R activation and blocking the activity of TM4SF4 using specific antibody can be a promising therapeutics against TM4SF4-overexpressing lung adenocarcinoma." (PMID 25344917, 2014). "In the present study, novel cancer-related targets of miR-223 were identified and verified in a LLC cell line, indicating that miR-223 functions as a tumor suppressor, which may fine-tune the activity of the IGF-1R pathway in lung cancer." (PMID 24137330, 2013). "EGFR mutant lung cancers with genetic alterations that activate the PI3K-AKT signaling pathway or IGF1R signaling may benefit from treatment with PI3K or AKT inhibitors or an IGF1R antibody, respectively, in combination with an EGFR TKI." (PMID 22970367, 2012).
lung cancer (continued). "Since elevated expression of IGF-1R increases the risk of breast, colon, prostate, and lung cancer, and blocking IGF-1R decreases cell growth and tumor formation, IGF-1R is increasingly recognized by the medical community as a relevant target for investigation in cancer research." (PMID 23071652, 2012). "Although these studies were not designed to investigate the activity according to NSCLC histologies or EMT status, these results suggest rational strategy to enrich for lung cancer patients that might benefit from treatment with anti-IGF-1R antibodies." (PMID 24212944, 2011). "Since pre-clinical studies may contribute to the decision-making process for advancing these therapies to clinical trials, various pre-clinical studies have investigated IGF-1R-targeted therapies in lung cancer models, using monoclonal antibodies and tyrosine kinase inhibitors." (PMID 38540176, 2024). "Therefore, targeting PRKCSH may be a promising therapeutic strategy for various tumors including IGF1R-related lung cancer." (PMID 38200153, 2024). "THRIL/ miR-99a/IGF1R axis might be a novel potential target in lung cancer." (PMID 37582734, 2023). "Notably, we clinically verified the PKM2-regulated expression of IGF-1R through immunohistochemical staining in a tissue microarray of 112 lung cancer patients, demonstrating a significant positive correlation (r = 0.5208, p < 0.0001) between PKM2 and IGF-1R expression." (PMID 34359752, 2021). "Moreover, IGF signaling has been previously involved in keeping human lung cancer cell stemness while IGF1R downregulation, in conjunction with INSR inhibition, was more effective in blocking IGF- and insulin-mediated signaling and growth in cancer cells compared to single-receptor targeting alone." (PMID 27861515, 2016). "As previous studies suggested that the inhibition of ALK and IGF1R pathways may potentiate chemotherapy and radiotherapy in lung cancer, crizotinib might be an effective additional therapeutic agent in patients with aggressive ARMS tumours that overexpress ALK, MET and IGF1R proteins." (PMID 26445453, 2015). "The binding prevents the translational inhibition of epidermal growth factor receptor (EGFR) and insulin-like growth factor 1 receptor (IGF1R), which both are essential cellular oncogenic proteins that drive carcinogenesis in human cancers such as lung cancer." (PMID 39736850, 2025). "Pathway analysis showed COPD–lung cancer overlaps in small GTPase signaling and starvation response, with blood‐specific enrichment for JUN kinase, IGF1R signaling, and autophagy, and tissue‐specific enrichment for endosomal transport and leukocyte chemotaxis." (PMID 41377765, 2025). "We have shown for the first time that paclitaxel upregulates circIGF1R in lung cancer cells by inducing RBFOX3 and downregulates IGF1R mRNA." (PMID 38191906, 2024). "IGF-1R, an RTK activated by IGF-1 and IGF-2, contributes to lung cancer by initiating pathways involved in cell proliferation and survival." (PMID 38540176, 2024). "In a study of a patient with anaplastic lymphoma receptor tyrosine kinase (ALK) fusion-positive lung cancer who had developed TKI resistance, combined ALK and IGF-1R inhibition improved therapeutic efficacy." (PMID 38540176, 2024). "In another study involving lung cancer cell lines A549 and H1299, PTL significantly impeded cell proliferation and migration by blocking the phosphorylation of insulin-like growth factor 1 receptor (IGF-1R), Akt, and forkhead box O3α (FoxO3α)." (PMID 39272454, 2024).
lung cancer (continued). "In our comprehensive study, we conducted molecular modelling analyses to identify potential drug candidates for targeting four key proteins involved in lung cancer: CDK2, SRC-2 domains of C-ABL, EGFR, and IGF-1R kinase." (PMID 38905286, 2024). "In this study, we focus on four proteins that play crucial roles in the context of lung cancer: human cyclin-dependent kinase-2 (CDK2), SRC-2 domains of C-ABL, epidermal growth factor (EGF), and insulin-like growth factor-1 receptor kinase (IGF-1R)." (PMID 38905286, 2024). "To investigate whether IGF1R/IR signaling is implicated in the associated development of pulmonary emphysemas and cancer, we analyzed FVB/N mice that were exposed to NB in accordance with the well-established protocol for lung cancer development (3 μmol each, twice weekly via oral gavage)." (PMID 38902841, 2024). "Hyperglycemia promotes the advancement of lung cancer through high levels of insulin receptor expression, and the IGF-1/IGF-1R pathway is known to play an essential role in the pathogenesis of lung cancer." (PMID 38468345, 2024). "Lung cancer (LC) is regarded as a fatal cancer, and insulin-like growth factor 1 (IGF1) and its receptor (IGF1R) have been found to play a key role in regulating tumor glycolytic metabolism." (PMID 38840891, 2024). "Some of the RTKs that were highly expressed in lung cancer cell lines are the Epidermal growth factor receptor (EGFR), fibroblast growth factor receptor 1 (FGFR1), insulin-like growth factor 1 receptor (IGF1R), and tyrosine-protein kinase Met (MET)." (PMID 36926328, 2023). "To examine the effect of EGFR and IGF1R on lung cancer cell motility, we performed a wound-healing assay on CL1-5 cells infected with EGFR or IGF1R shRNAs." (PMID 37880793, 2023). "In lung cancer cells, THRIL regulated IGF1R through miR-99a and then affected the proliferation, migration, invasion, and apoptosis." (PMID 37582734, 2023). "We next considered the different gradings of lung cancer and discovered that patients with LUAD at stage G2 had higher levels of IGF1R in their peri-tumoral region of the lung compared to the control regions." (PMID 35574343, 2022). "With forced EGFR−AS1 expression promoting NSCLC cell proliferation and chemoresistance via regulating miR-223/IGF1R axis, univariate and multivariate analyses reported EGFR−AS1 as an independent prognostic marker in lung cancer." (PMID 35463380, 2022). "The present study demonstrated that IGF-1R and Livin genes are highly expressed in CRC and the other cancer types, such as cholangiocarcinoma and kidney, liver, and lung cancers, through the TCGA database." (PMID 35931997, 2022). "It has been reported that insulin-like growth factor 1 (IGF-1), the ligand of the IGF-1 receptor (IGF-1R), is highly expressed in the TME of the liver metastasis, and the signaling from IGF-1R promotes the tolerance to osimertinib in EGFR-positive lung cancer." (PMID 36140210, 2022). "Earlier reports have indicated that CFIm25 promotes the protein expression of oncogenes, including IGF1R, by regulating their APA, thereby enhancing the proliferation and inhibiting the apoptosis of lung cancer cells." (PMID 35487956, 2022). "By targeting IGF1, IGF1R and PIK3R1 this miRNA induces cell cycle arrest and reduces migration of lung cancer cells while acting as a tumour suppressor in a xenograft mouse model." (PMID 34547721, 2021). "While combined mTOR, IGF1R, and MEK inhibition shows significant tumor regression in K-RasG12C–driven lung cancer mouse models, replacing the MEK inhibitor with a K-RasG12C inhibitor in combination demonstrates greater efficacy, specificity, and tolerability." (PMID 34222333, 2021). "Supporting a requirement for RIT1, AURKA, IGF1R, and FURIN in the proliferation of RIT1-mutant lung cancer, knockout of each gene significantly reduced cell proliferation of H2110iCas9 compared to cells expressing a non-targeting control guide (sgNTC)." (PMID 34373451, 2021).